CRB3 (crumbs cell polarity complex component 3)
Diseases named in the same sentence as CRB3 in open-access papers (continued):
Sharing a sentence is not in itself a finding about the gene and the disease.
tumor (12 papers, 2015 to 2025). "CRB3 expression is negatively associated with tumor malignancy." (PMID 28436991, 2017). "Targeting anti-tumor CP protein CRB3 can inhibit tumor growth and lung metastasis, and LKB1 overexpression suppresses growth, microvascular density, and lung metastasis in LKB1-deficient MDA-MB-435 cells." (PMID 40057606, 2025). "For example, restoring murine Crb3 improved cell polarity and reduced tumor cell properties in kidney epithelial cells." (PMID 39859373, 2025). "CRB3, an important apical protein, is significantly reduced in various tumor cells and tissues, as well as promotes metastasis and tumor formation in nude mice." (PMID 37737843, 2023). "Based on the multivariable Cox models, GET4 and CRB3 were independent prognostic factors after adjusting for tumor stage and patient age and sex." (PMID 33850477, 2021). "Immunohistochemistry analysis showed that CRB3 expression was reduced in tamoxifen‐resistant tissues compared to their matched primary tumour counterparts." (PMID 29602199, 2018). "Consistent with the findings of the in vitro experiments, the MCF7 tumours grew more slowly than CRB3‐knockdown MCF7 tumours." (PMID 29602199, 2018). "We hence evaluated a tumour cell population with these markers upon changes of CRB3 expression levels." (PMID 29602199, 2018). "Bioinformatics analyses in tumor cell lines and patient samples confirm a positive correlation in CRB3 and EPB41L4B expression." (PMID 30440051, 2018). "Previously, it was demonstrated that direct perturbation of CRB3 can lead to phenotypic changes that facilitate tumor progression, our study agree with previous findings, but support that CRB3 most likely affected migration and invasion through CSC regulation." (PMID 28436991, 2017). "In addition to verifying the effect of Crb3 deletion on promoting proliferation and inhibiting apoptosis in vivo, we detected these markers in primary tumor tissue from PyMT-WT and PyMT-cKO-Crb3 mice." (PMID 37737843, 2023). "Data from TCGA dataset in our study also confirmed this finding, and evidence from our study showed that CRB3 might be a broad-spectrum tumor suppressor gene according to its positive gene effect scores across different cell lines." (PMID 33850477, 2021). "Based on these data, CRB3 decreased tumour growth and increased tumour cell apoptosis in vivo." (PMID 28079891, 2017). "These expression patterns are consistent with the reported role of CRB3 as a tumor suppressor." (PMID 28436991, 2017). "CRB3 mRNA expression in MCF 10A cells was remarkably 105-fold that of the tumor cells." (PMID 28436991, 2017). "Furthermore, CRB3 seemed to be a potential broad tumor suppressor gene, while GET4 might be a ccRCC preferential dependency gene with a ligandable structure that could facilitate future drug development." (PMID 33850477, 2021). "B4GALT4, BCL2L1, COPG1, CRB3, GET4, and TFRC showed almost the same expression levels between tumor and normal tissues." (PMID 33850477, 2021). "In the univariable Cox analysis, clinical tumor stage, age, and the expression levels of NFE2L2, ITGAV, GET4, FERMT2, CRB3, CDH2, and BCL2L1 were prognostic factors for OS." (PMID 33850477, 2021). "Crumbs homolog 3 (CRB3), a member of the CRB polarity complex, has been reported to act as a tumor suppressor." (PMID 28436991, 2017). "To address the general significance of this finding, we examined whether the relationship between CRB3 and EPB41L4B expression is observed more broadly in immortalized breast epithelial cell lines and in tumor cell lines derived from patient samples." (PMID 30440051, 2018). "CRB3, the human orthologue of CRB, is a tumour suppressor in mammalian epithelial cells." (PMID 29602199, 2018). "CRB3 expression was correlated with tumour size but not with age, histological grade, clinical stage or lymph node involvement." (PMID 28079891, 2017).
tumor (continued). "Compared to cells in tumor 3 that expressed increased epithelial markers like CDKN2A, CRB3, KRT13, and KRT6, tumor cells in metastatic LN exhibited high expression of mesenchymal markers like CDH3, ECM1, TGFB1, WARS, and VIM, indicating that tumor metastasis was related to EMT." (PMID 36569924, 2022). "CRB3 appeared to be a potential common tumor suppressor gene according to the RNAi screening results in which most gene effect scores were positive, and RCC lineage, MSI state, and tumor type did not appear to be associated with the effect of CRB3 knockdown." (PMID 33850477, 2021). "We speculated that CRB3 regulated TAZ through AMOT/p130, and our results suggest that TAZ/β-catenin was the key downstream targets of CRB3, whose activities sustained the self-renewal and tumor-initiation capacities of breast CSCs." (PMID 28436991, 2017). "Although the knockout of Crb3 is not sufficient to cause nuclear enrichment of β-catenin and excessive proliferation at E18.5, long-term lack of Crb3 expression in the adult intestinal epithelium could favor tumor formation." (PMID 26631503, 2015). "Furthermore, after 2 weeks of treatment with TAM, the tumour sizes and weights decreased remarkably in the mice injected with MCF7 cells compared with those in the CRB3‐knockdown MCF7 cells group, and CRB3‐knockdown MCF7 cells were more resistant to tamoxifen than control MCF7 cells." (PMID 29602199, 2018).
cancer (8 papers, 2011 to 2022). A tumor composed of atypical neoplastic, often pleomorphic cells that invade other tissues. "Our results may provide a clue about the relationship between the loss of CRB3 expression and the loss of contact inhibition, a hallmark of cancer cells." (PMID 28079891, 2017). "Recent studies have suggested a role for CRB3 in regulating cancer stem cell properties of mammary epithelial cells via Pals1/PATJ." (PMID 30440051, 2018). "Studies have demonstrated that CRB3 plays a central role in cancers such as CRC." (PMID 35012593, 2022). "Thus, increased CRB3 expression reduced cancer stem cell‐like features of tamoxifen‐resistant cells by inhibiting the β‐catenin signalling pathway." (PMID 29602199, 2018). "Conversely, CRB3-overexpressing cells formed carcinomas displaying less nuclear atypia." (PMID 28436991, 2017). "Theoretically, the high CRB3 expression in normal tissues (except kidney), such as stomach, lung, and skin, that indicates its potential protective function could also exist in cancer from these tissue sites, but this conclusion needs further assessment and validation in the future." (PMID 33850477, 2021). "To further examine whether CRB3 downregulation conferred cancer stem cell traits through activation of β‐catenin signalling in tamoxifen‐resistant cells, we assessed whether CRB3 up‐regulation could reduce β‐catenin expression and affect subcellular localization of β‐catenin protein." (PMID 29602199, 2018). "Interestingly, we identified statistically significant co-expression of CRB3 with EPB41L4B and/or EPB41L5 in several microarray studies of cell line panels, across the entire cell line panel of the Cancer Cell Line Encyclopedia, as well as a study of 21 primary human mammary epithelial cell lines." (PMID 30440051, 2018).
infection (1 paper, 2016). The state of being infected such as from the introduction of a foreign agent such as serum, vaccine, antigenic substance or organism. "In addition, using co-infection with both Crb3 shRNA and YAP shRNA adenoviruses, we reduced YAP expression in the over-elongating Crb3-silenced cells." (PMID 27435623, 2016).
peripheral neuropathies (1 paper, 2016). "We conclude that the Crb3/Hippo/YAP pathway is a major regulator of myelination in peripheral nerves and we propose that defects in YAP activation underlie peripheral neuropathies with reduced internodal length." (PMID 27435623, 2016). "Here authors show that peripheral myelin growth is orchestrated by the Crb3/Hippo/YAP pathway, and that defects in YAP activation may underlie peripheral neuropathies caused by shorter myelin." (PMID 27435623, 2016). "Our data therefore suggest that peripheral neuropathies with reduced internodal length are due to defects in the expression of YAP in the Schwann cell nucleus and it may be possible to correct suboptimal internodal lengths by artificially promoting YAP activity via manipulation of Crb3." (PMID 27435623, 2016).
CRB3 also shares sentences with these, for which no sentence is quoted: colorectal carcinoma (3 papers); Anophthalmia (1); celiac disease (1); COVID-19 (1); oral squamous cell carcinomas (1); renal cyst (1); respiratory distress syndrome (1).